ENPP1 (ectonucleotide pyrophosphatase/phosphodiesterase 1)
Diseases named in the same sentence as ENPP1 in open-access papers (continued):
Sharing a sentence is not in itself a finding about the gene and the disease.
Insulin resistance (continued). "Some Enpp1 121Gln polymorphisms are associated with higher risk of hyperlipidemia and liver injury in patients with MAFLD with other scholars showing that Enpp1 aggravates insulin resistance." (PMID 39972484, 2025). "In addition, the effects of Enpp1 on the development of obesity and insulin resistance in MAFLD mice were explored, focusing on mechanisms associated with liver lipid accumulation." (PMID 39972484, 2025). "It is possible that degrading ENPP1 to eliminate this interaction could have therapeutic relevance to insulin resistance and type 2 diabetes." (PMID 37400538, 2024). "Similarly, ENPP1 overexpression stimulates severe whole-body insulin resistance, obesity, and type 2 diabetes." (PMID 39199273, 2024). "UA can also inhibit the trigger of insulin signaling at receptor level through an ectonucleotide pyrophosphatase / phosphodiesterase 1 (ENPP1) recruitment, and induce insulin resistance by NOD-like receptor family pyrin domain containing 3(NLRP3) inflammasome activation." (PMID 36464722, 2022). "The binding of ENPP-1 to the α-domain of the insulin receptor prevents the activation of insulin signaling with subsequent GLUT-4 storage resulting in insulin resistance and hyperglycemia that could result in DM." (PMID 35055468, 2022). "Single nucleotide polymorphisms (SNPs) in obesity-related genes, such as ectonucleotide pyrophosphatase phosphodiesterase 1 (ENPP1) and adiponectin (ADIPOQ), potentially increase the risk of insulin resistance, the most common metabolic dysregulation related to obesity." (PMID 34208364, 2021). "YLNKYLGDV could potentially be processed from transmembrane glycoprotein ectonucleotide pyrophosphatase phosphodiesterase 1 (ENPP1) protein, a key player involved in inhibiting insulin receptor signaling and the development of insulin resistance." (PMID 32425926, 2020). "We then speculated that this UA effect might be mediated by an increased binding of IR to ENPP1, a well-known inhibitor of IR auto-phosphorylation that has been shown to be overactive in condition of insulin resistance." (PMID 29619007, 2018). "This mutual influence and regulation between insulin and ENPP1 seem to further suggest that ENPP1 might contribute to insulin resistance through the down-regulation of insulin action and promoting hepatic gluconeogenesis." (PMID 29513794, 2018). "On the other hand, experimental results have indicated that ENPP1 might contribute to insulin resistance." (PMID 29513794, 2018). "Mutations in the ENPP1 gene have been associated with ‘idiopathic’ infantile arterial calcification 52, ossification of the posterior longitudinal ligament of the spine OPLL 53, hearing loss 54 and insulin resistance." (PMID 27406238, 2016). "The ENPP1 gene was significantly correlated with insulin resistance in 1999." (PMID 27337171, 2016). "This may explain, at least in the case of increase Enpp1 expression in skeletal muscle, some of the insulin resistance in our mutant mice (reviewed)." (PMID 23826075, 2013). "We have found that ENPP1 K121Q, a common genetic polymorphism that determines increased ENPP1-insulin receptor interaction, can be associated with insulin resistance in absence of obesity." (PMID 17849011, 2007). "ENPP1 expression was found down-regulated during 3T3-L1 maturation, and over-expression of human ENPP1 in 3T3-L1 (pQCXIP-ENPP1 vector) resulted in adipocyte insulin resistance and in defective adipocyte maturation." (PMID 17849011, 2007). "This study was performed to evaluate whether ENPP1 is regulated during adipogenesis and whether over-expression in adipocytes can affect adipocyte maturation, a potential novel mechanism of ENPP1-related insulin resistance." (PMID 17849011, 2007). "Moreover, Enpp1 overexpression improve glucose tolerance and insulin resistance in mice." (PMID 39972484, 2025).
Insulin resistance (continued). "There are pieces of evidence that ENPP1, binding to α-subunit of IR (IRα), impairs IR signaling by inhibiting its autophosphorylation, and consequently insulin receptor substrate-1 phosphorylation and glucose transport contributing, thus, to the development of insulin resistance." (PMID 29619007, 2018). "Individuals with impaired glucose tolerance also tended to have decreased liver ENPP1 protein, and the pattern of liver ENPP1 protein abundance in the IGT and T2DM groups is likely caused by high circulating levels of insulin as both groups had moderate to severe insulin resistance respectively." (PMID 25539584, 2014). "ENPP1 may contribute to insulin resistance through its inhibitory action on insulin signalling." (PMID 25539584, 2014). "Consistently with its dual function, ENPP1 inactivating mutations caused generalized arterial calcification of infancy (GACI;), and over-expression of ENPP1 has been found to be associated with human insulin resistance in non-insulin-dependent diabetes mellitus." (PMID 21738662, 2011). "Collectively, our findings suggest that liver-specific Enpp1 knockout in mice fed an HFD exhibited exacerbated obesity and insulin resistance." (PMID 39972484, 2025). "Alterations in the ectonucleotide pyrophosphatase phosphodiesterase 1 (ENPP1) gene were reported as one of the genetic factors involved in obesity and insulin resistance." (PMID 34208364, 2021). "This suggests improvement of liver insulin resistance is central to remission of T2DM after RYGB surgery and provides a unique opportunity to examine the role of ENPP1 in these conditions." (PMID 25539584, 2014). "The individuals who had resolution of insulin resistance and remission of T2DM following RYGB had a mean 2.7 (95% CI, 1.8 to 4.0) fold increase in liver ENPP1 protein abundance." (PMID 25539584, 2014). "Ectonucleotide pyrophosphatase phosphodiesterase 1 (ENPP1, also known as PC-1) has been recently reported to be involved in the pathogenesis of insulin resistance and related diseases." (PMID 17849011, 2007). "Although our work does not discount the possibility that ENPP1 contributes to insulin resistance, it does add another dimension that will have to be considered in future work exploring the influence ENPP1 has on liver insulin signalling." (PMID 25539584, 2014). "We measured levels of ENPP1 mRNA expression and protein abundance in individuals with and without T2DM and again after resolution of insulin resistance and remission of T2DM." (PMID 25539584, 2014). "Neither group had significant changes in liver ENPP1 gene expression after RYGB surgery (data not shown), suggesting that post translational regulation is more important in the regulation of ENPP1 protein level with change in insulin resistance and remission of diabetes." (PMID 25539584, 2014).
Generalized arterial calcification of infancy (37 papers, 2012 to 2025). "ENPP1 variants cause Generalized Arterial Calcification of Infancy (GACI), a rare genetic disorder characterized by ectopic calcification, intimal proliferation, and stenosis of large- and medium-sized arteries." (PMID 38994980, 2024). "Pathogenic variants in the ENPP1 cause generalized arterial calcification of infancy (GACI [OMIM 208000])." (PMID 39538190, 2024). "Generalized arterial calcification of infancy (GACI) is a rare disorder caused by ENPP1 or ABCC6 variants." (PMID 34355424, 2021). "Recently, generalized arterial calcification of infancy (GACI) has been linked to ectonucleotide pyrophosphatase/phosphodiesterase 1 (ENPP1) together with some cases of pseudoxanthoma elasticum (PXE)." (PMID 31828085, 2019). "For example, generalized arterial calcification of infancy (GACI) is caused by mutations in the enzyme ecto-nucleotide pyrophosphatase/phosphodiesterase-1 (eNPP1), preventing the hydrolysis of ATP into pyrophosphate (PPi)." (PMID 30713844, 2018). "Generalized arterial calcification of infancy (GACI) is an autosomal recessive disorder caused by mutations in the ENPP1 gene." (PMID 28402956, 2017). "Generalized arterial calcification of infancy (GACI) is associated with biallelic mutations in ENPP1 in the majority of cases, whereas mutations in ABCC6 (ATP-binding cassette subfamily C number 6) are known to cause pseudoxanthoma elasticum (PXE)." (PMID 23269929, 2012). "Loss-of-function mutations in ENPP1 lead to generalized arterial calcification of infancy (GACI)." (PMID 33815294, 2021). "Autosomal recessive hypophosphatemic rickets type 2 (ARHR2) and generalized arterial calcification of infancy (GACI) occur secondary to biallelic ectonucleotide pyrophosphate/phosphodiesterase 1 (ENPP1) loss-of-function pathogenic variants." (PMID 41445557, 2025). "Mutations in both alleles of the ENPP1 are associated with generalized arterial calcification of infancy (GACI1: OMIM #208000) and autosomal recessive hypophosphatemic rickets type 2 (ARHR2: OMIM #613312)." (PMID 40535334, 2025). "Generalized arterial calcification of infancy (GACI) and autosomal recessive hypophosphatemic rickets type 2 (ARHR2) are age-related phenotypes of the rare genetic mineralization disorder, ENPP1 Deficiency, which evolve on a phenotypic continuum." (PMID 40176950, 2025). "Deficient generation of PPi from extracellular ATP, due to mutations in the gene encoding ectonucleotide pyrophosphatase/phosphodiesterase 1 (ENPP1), leads to a disease known as generalized arterial calcification of infancy (GACI)." (PMID 33768090, 2021). "Pathogenic variants in the ENPP1 gene (ectonucleotide pyrophosphatase/phosphodiesterase 1; OMIM∗173335), the gene associated with Generalized Arterial Calcification of Infancy (GACI; OMIM#208000), were also found to cause PXE, although less frequently." (PMID 34169069, 2021). "In light of the knowledge derived from studies of generalized arterial calcification of infancy (GACI), a rare disease characterized by low [PPi]pl due to an inactivating mutation of ENPP1, we measured NPP plasma activity which was within normal values." (PMID 33425894, 2020). "Mutation of eNPP1 results in generalised arterial calcification of infancy (GACI), which is characterised by calcification of arteries, and eNPP1-null mice also develop ectopic artery calcification." (PMID 28570619, 2017). "Deleterious mutations in human ABCC6, ENPP1, NT5E genes cause PXE, generalized arterial calcification of infancy (GACI), and arterial calcification respectively." (PMID 26375467, 2015). "Generalized arterial calcification of infancy (GACI) is an autosomal recessive disorder of spontaneous infantile arterial and periarticular calcification which is attributed to mutations in the ectonucleotide pyrophosphatase/phosphodiesterase 1 (Enpp1) gene." (PMID 25975272, 2015).
Generalized arterial calcification of infancy (continued). "Generalized arterial calcification of infancy (GACI), an autosomal recessive disorder caused by mutations in the ENPP1 gene, manifests with extensive mineralization of the cardiovascular system." (PMID 25479107, 2014). "Generalized arterial calcification of infancy (GACI) is a fatal human disease, and the majority of cases are thought to be caused by mutations in ENPP1." (PMID 24906371, 2014). "INZ-701 is a recombinant human ENPP1-Fc fusion protein, which is currently being evaluated in clinical trials to treat patients with generalized arterial calcification of infancy (GACI) and autosomal recessive hypophosphatemic rickets type II (ARHR2), also known as ENPP1 deficiency." (PMID 38994980, 2024). "Children suffering from generalized arterial calcification of infancy (GACI), caused by a mutation of the gene Enpp1, which is responsible for the conversion of ATP into AMP and PPi, could also benefit from PPi supplementation therapy." (PMID 32074140, 2020). "Generalized Arterial Calcification of Infancy (GACI) is a heritable ectopic mineralization disorder resulting in diffuse arterial calcifications and/or stenosis, mostly caused by mutations in the ENPP1 gene." (PMID 29976176, 2018). "Generalized arterial calcification of infancy (GACI) is a rare, life-threatening disorder caused by loss-of-function mutations in the gene encoding ectonucleotide pyrophosphatase phosphodiesterase 1 (ENPP1), which normally hydrolyzes extracellular ATP into AMP and pyrophosphate (PPi)." (PMID 30158213, 2018). "Various disorders including pseudoxanthoma elasticum (PXE) and generalized arterial calcification of infancy (GACI), which are caused by inactivating mutations in ABCC6 and ENPP1, respectively, present with extensive tissue calcification due to reduced plasma pyrophosphate (PPi)." (PMID 28701330, 2017). "Idiopathic infantile arterial calcification (IIAC), also known as generalized arterial calcification of infancy (GACI), is a heritable ectopic mineralization disorder that results in diffuse arterial calcifications and or stenosis, which are attributed to mutations in the ENPP1 gene." (PMID 35003211, 2021). "Generalized Arterial Calcification of Infancy (GACI, OMIM 208000), also known as idiopathic infantile arterial calcification, is a heritable ectopic mineralization disorder resulting in diffuse arterial calcifications mostly caused by mutations in the ENPP1 gene." (PMID 29976176, 2018). "It has been reported that the inactivating mutations of the ectonucleotide pyrophosphatase/phosphodiesterase 1 (ENPP1) gene can lead to Generalized Arterial Calcification of Infancy 1 (GACI1) (OMIM #208000) and Autosomal-Recessive Hypophosphatemic Rickets 2 (ARHR2) (OMIM # 613312)." (PMID 40270714, 2025). "Generalized arterial calcification of infancy (GACI), a widely calcified syndrome of the whole body caused by inactivating mutations in Enpp1, is charactered by reduced plasma PPi (virtually no PPi in GACI patients’ blood) and AMP." (PMID 37370114, 2023). "Generalized arterial calcification of infancy, an autosomal-recessive genetic disorder, causes the premature onset of arterial calcification due to a functional absence of the NPP1-encoding gene (ENPP1) leading to a decrease in NPP1 activity and thus a reduction in the generation of PPi." (PMID 33076470, 2020).
breast carcinoma (35 papers, 2013 to 2026). "Here, we found that a mouse harboring a point-mutation in ENPP1 rendering it unable to degrade cGAMP is resistant to breast cancer metastasis in a STING-dependent manner." (PMID 38117852, 2023). "Clinical data suggest ENPP1 expression in primary breast cancer tissues is associated with malignant potential and response to chemotherapy." (PMID 29386520, 2018). "Here the authors show that microRNA-27b mediates generation of a side-population of breast cancer stem cells, in part by regulating the protein ENPP1, which has been previously linked to the development of diabetes." (PMID 26065921, 2015). "Moreover, upregulated ENPP1 has been associated with the promotion of cancer cell migration and bone metastasis in breast cancer." (PMID 36761762, 2023). "More importantly, ENPP1 is also associated with poor response to chemotherapy in breast cancer." (PMID 36761762, 2023). "Furthermore, the ISPY 2 Trial data nominated ENPP1 as a potential companion diagnostic biomarker: ENPP1-low breast cancer patients are significantly more likely benefit from anti-PD-1 and PARPi therapies than their ENPP1-high counterparts." (PMID 38117852, 2023). "To determine whether ENPP1 expression is causally linked to poor prognosis in breast cancer, we sought to perform mechanistic studies in mouse models." (PMID 38117852, 2023). "Likewise it was shown that loss of microRNA-27b contributed to breast cancer stem cell generation by activating ENPP1." (PMID 29386520, 2018). "Finally, the diagnostic value of ENPP1 expression was evaluated by a qRT–PCR analysis of a subset of primary human breast cancer specimens." (PMID 26065921, 2015). "Furthermore, our clinical data suggest ENPP1 expression in primary breast cancer tissues is associated with malignant potential and response to chemotherapy." (PMID 26065921, 2015). "Enpp1 is located at 6q22-q23, a region reportedly amplified in breast cancer, and its mutation has been associated with several disorders including infantile arterial calcification, ossification of the posterior longitudinal ligament of the spine, and insulin resistance." (PMID 23861746, 2013). "For instance, preclinical evidence indicates that ENPP1, secreted from primary breast cancer, can induce endothelial cell dysfunction by impairing insulin signaling and its downstream AKT/GSK3β/β-catenin pathway." (PMID 41219968, 2025). "A recent study found that the enzyme ectonucleotide pyrophosphatase/phosphodiesterase 1 (ENPP1) secreted by a human epidermal growth factor receptor 2-positive (HER2+) breast cancer increased BBB permeability to facilitate brain colonization." (PMID 40806198, 2025). "Only EMT6 mammary carcinoma cancer cells expressed Enpp1 in agreement with human data that Enpp1 is more abundant in breast cancer cells." (PMID 39622844, 2024). "Adenosinergic metabolites produced by high ectonucleotide pyrophosphatase/phosphodiesterase 1 (Enpp1) expression in breast cancer enhance the expression of haptoglobin, which recruits PMN-MDSCs." (PMID 38609997, 2024). "Many studies have shown that ENPP1 is overexpressed in diverse cancer types such as lung cancer, breast cancer, and ovarian cancer." (PMID 36761762, 2023). "Together, we put forward a model that boosting extracellular cGAMP–STING signaling is the major mechanism of action of ENPP1 inhibition in mounting immune protection against breast cancer." (PMID 38117852, 2023). "We performed orthotopic implantation of Enpp1-knockout 4T1 murine breast cancer cells overexpressing either WT ENPP1 (ENPP1WT-OE) or catalytically dead ENPP1 (ENPP1T238A-OE) into WT mice." (PMID 38117852, 2023). "Circulating breast cancer cells expressed high ectonucleotide pyrophosphatase/phosphodiesterase 1 (ENPP1) after radiation, which increased haptoglobin expression." (PMID 38023616, 2023). "High expression levels of ENPP1 have been observed in many cancer types such as lung cancer, ovarian cancer, and breast cancer." (PMID 36761762, 2023).